CLDN1 (claudin 1)
Diseases named in the same sentence as CLDN1 in open-access papers (continued):
Sharing a sentence is not in itself a finding about the gene and the disease.
colon carcinoma (84 papers, 2007 to 2025). "Claudin-1 is one of the tight junction proteins that regulate permeability in the intestine, and its expression has been associated with a reduction in colon cancer." (PMID 41009619, 2025). "In this context, CLDN1 expression was linked to enhanced invasiveness and metastasis of multiple malignancies, such as gastric carcinoma and colon cancer." (PMID 36672179, 2023). "A decrease or loss of claudin 1 was strongly associated with poor patient prognosis for colon cancer." (PMID 36714681, 2023). "As a tight junction protein, claudin-1 was confirmed to be associated with Src/p-Src in colon cancer cells in modulating cell anoikis." (PMID 33784242, 2021). "Increased expression of CLDN-1 is associated with the progression and metastasis of colon carcinoma." (PMID 31952355, 2020). "The progression of colon cancer has been linked with the dysregulation of the CLDN-1 expression causing disorganization of the tight junction fibrils leading to increased paracellular permeability." (PMID 31952355, 2020). "In Hahn-Strömberg V’s study, they found that CLDN1 rs9869263 genotype was related to risk of colon cancer and polymorphisms in CLDN7 were associated with differentiation and age of colon cancer." (PMID 30910845, 2019). "Specifically, ectopic APC expression decreases CLDN1 expression in Wnt-activated APC-deficient colon cancer cells, and CLDN1 requires its TCF-binding site for transcriptional activation." (PMID 28757546, 2017). "As an example, claudin-1 expression was found to be reduced in breast and in colon cancer; in colon cancer it was also associated with recurrence and poor prognosis." (PMID 28316601, 2017). "One study did an analysis of the allele frequencies on three common single nucleotide polymorphisms (SNPs) in the genes for claudin-1 and 7 in colon cancer patients." (PMID 27547510, 2016). "Low expression of claudin-1 is associated with poor patient prognosis in several cancers, including stage II colon cancer and prostate cancer, and it is an independent predictor of tumor recurrence in both cancer types." (PMID 24009024, 2013). "In this regard, expression of claudin-1, a key constituent of TJs, is highly increased in colon cancer and is causally associated with the tumor growth and progression." (PMID 22719836, 2012). "Such a notion gains support by published findings from ours and other laboratories that increased claudin-1 expression in human colon cancer cells bears causal correlation with the APC mutation." (PMID 22719836, 2012). "Claudin-1 expression is highly increased in colon cancer and is causally associated with the tumor growth and progression." (PMID 22719836, 2012). "It is further worthy here to note that in colon cancer, dysregulated claudin-1 expression associates with the tumor progression and metastasis." (PMID 22719836, 2012). "It is further interesting that colon cancer cells that expressed claudin-1 (HT29, SW480, and SW620) all harbor mutations in APC and have activated β-catenin/Tcf signaling." (PMID 20671913, 2010). "Interestingly, loss of CLDN1 in colon tumors was significantly associated with larger tumor size, vascular invasion, deeper invasion, and higher lymph node metastasis." (PMID 40687428, 2025). "Interestingly, SW480 colon cancer cells engineered to overexpress Claudin-1 formed tumors at a significantly higher rate and caused multiple liver metastases compared with the control cells." (PMID 31467400, 2019). "Another SNP, the rs17501976 polymorphism in CLDN1 was also shown to impact colon cancer risk." (PMID 27649506, 2016). "Also, induction of epithelial differentiation in colon cancer cells using Histone deacetylase (HDAC) inhibitors associated with a specific decrease in claudin-1 expression among claudin family members." (PMID 22719836, 2012). "Moreover, CLDN1 has been linked to colon cancer tumorigenesis." (PMID 40426863, 2025).
colon carcinoma (continued). "However, it remains unclear if modulation of claudin-1 expression even in normal colonic epithelial cells would serve a tumor promoting role, under conditions permissive of colon cancer growth, and the underlying molecular mechanisms." (PMID 24997475, 2014). "Overexpression of CLDN1 promotes epithelial–mesenchymal transition, metastasis, resistance to anoikis, and chemotherapy in colon cancer cells through a direct interaction with ephrin type-A receptor 2 tyrosine kinase." (PMID 40361399, 2025). "In colon cancer, nuclear localization of CLDN1 was noted frequently, and manipulation of CLDN1 expression significantly affected the EMT marker changes and distant metastasis during in vitro and in vivo studies." (PMID 38731853, 2024). "CLDN1 expression was also shown to be regulated through the modulation of mRNA stability in colon cancer cells in a histone-deacetylase-dependent mechanism." (PMID 38731853, 2024). "CLDN1 upregulation after exposure to conventional chemotherapies used in colon cancer is, at least in part, functionally related to activation of the MAPKp38/GSK3β/Wnt/β-catenin pathway." (PMID 39065798, 2024). "In another study analyzing the role of claudin-1 in adenoma formation in adenomatous polyposis coli (APC) in mice, APC-Cldn1 mice showed significantly increased colonic tumor growth, size, and decreased survival." (PMID 37627123, 2023). "The pathway has been shown to significantly promote the expression of claudin-1 in colonic cancer cells." (PMID 37627123, 2023). "In fact, CLDN1 has been described as a strong prognostic indicator of disease recurrence and poor patient survival in stage II colon cancer." (PMID 36672179, 2023). "For polypoid and flat precancerous lesions, Rabinsky and colleagues studied the overexpression of Claudin-1 in precancerous lesions of colon cancer and carried out near-infrared real-time imaging verification." (PMID 37781571, 2023). "In the present study we provide further experimental data suggesting a role of CLDN1 in the resistance of colon cancer cells to chemotherapy." (PMID 37041570, 2023). "While some studies link increasing CLDN1 expression to the growth and spread of colon cancer, others believe that low CLDN1 levels are a standalone predictor of a poor prognosis." (PMID 36620607, 2022). "The migration ability of colon cancer cells is enhanced by the upregulation and internalization of CLDN1 via the EGFR/PKC/CLDN1 signaling pathway." (PMID 36620607, 2022). "Previous studies demonstrated that the Wnt signaling pathway promoted CLDN1 expression and enhanced colon cancer cell proliferation, invasion and metastasis." (PMID 36620607, 2022). "We next focused directly on β-catenin, since it has been reported as necessary for SOX17 transcription of FOXA1 and associated with regulating the transcription factor ZEB-1 by the tight junction protein Claudin-1 in colon cancer cells." (PMID 33669586, 2021). "Nuclear CLDN1 localization was described for colon cancer cells and seems to modulate metastatic behaviour and also to be pivotal for aggressiveness of thyroid carcinoma." (PMID 33386991, 2021). "The nucleus and cytoplasm of colon carcinoma cells and metastatic lesions showed intensified CLDN-1 expression." (PMID 31952355, 2020). "In colon cancer cells, CLDN-1 decreases the expression of E-cadherin by upregulating ZEB-1 repressor resulting in invasion and reduction of anoikis." (PMID 31952355, 2020). "Studies have shown that reduced expression of claudin-1 is a predictor of poor prognosis and reduced disease-free survival, and that knockdown of claudin-1 expression in colon cancer cell lines significantly increase cell invasiveness." (PMID 32408894, 2020). "In colon cancer cells, claudin-1 mRNA stability is modulated by HuR and TTP26, and TTP and HuR have been shown to regulate IL-17 expression in multiple immune cell types via mRNA destabilization." (PMID 32487989, 2020).
colon carcinoma (continued). "The TCGA results indicated that SPIB, KRT24, PHLPP2, PLP1, BEST4, CA7, and C11orf86 were all downregulated, while KRT80, SLC39A10, AJUBA, FOXQ1, and CLDN1 exhibited upregulated levels in colon cancer." (PMID 32633726, 2020). "Claudin-1 up-regulated in metastasis tissues of colon cancer, by Mislocalization to the cytoplasm and cell nucleus." (PMID 31700829, 2019). "In contrast to claudin-1, claudin-7 has an inverse role on EMT, wherein it causes mesenchymal to epithelial transformation (MET) in Rab25 dependent manner to combat colon cancer." (PMID 31861759, 2019). "Our results showing the elevated expression of claudin-1, −3 and −4, EpCAM, E-cadherin in colon cancer were consistent with earlier studies." (PMID 30289336, 2019). "Caudal homeobox proteins (Cdx1 & Cdx2) and GATA binding protein 4, GATA4) are known activators of claudin-1 promoters in colon cancer." (PMID 31861759, 2019). "For example, the PDZ-binding motif of Claudin-1 has been shown to recruit Src in a complex with ZO-1 to confer resistance to anoikis in colon cancer." (PMID 30692208, 2019). "Claudin-1 and -7 have proved to have an inverse role in colon cancer, wherein claudin-1 elevates the metastasis of colon cancer cells." (PMID 31861759, 2019). "For example, the PDZ-binding motif of Claudin-1 is required to enable anoikis resistance in colon cancer cells by recruiting Src into a complex with ZO-1." (PMID 30692208, 2019). "When animals injected with colon cancer cells subcutaneously were imaged using claudin-1 antibody conjugated LI-COR IR800DyeCW through a LI-COR Pearl Trilogy Fluorescence Imaging System, the system was able to target tumors specifically." (PMID 31861759, 2019). "In colon cancer, claudin-1 was observed to be having transformative and metastatic potential while claudin-2 overexpression has been shown to be associated with colon carcinogenesis." (PMID 30728783, 2018). "It has been observed that caudal-related homeobox (Cdx) transcription factors regulate claudin-1 gene expression in human colon cancer cells and functional crosstalk with Wnt-signaling pathway was found to be important for this regulation." (PMID 30728783, 2018). "The results of a previous study showed that CDX2 overexpression in the colon cancer cell line SW480 improved the Claudin-1 gene promoter activity by 6-fold but only prompted a 4-fold increase in HCT116 cells." (PMID 27121315, 2016). "For instance, in colon cancer, claudin-1 was shown to promote transformation as well as metastatic behavior." (PMID 27547510, 2016). "Colon carcinoma cells show an increase in the cytoplasmic expression and nuclear localization of claudin-1 in primary tumours and metastases and knock-down of claudin-1 expression in cultured cell lines inhibits cell migration." (PMID 26573531, 2015). "Another interesting finding recently reported in colon cancer, was that CLDN1 protected cells from anoikis in suspension." (PMID 25544763, 2015). "CLDN1 directly regulated cell transformation and interfered cell behavior and survival in colon cancer." (PMID 25544763, 2015). "Claudin-1 regulated cell anoikis in colon cancer in a manner of regulating E-cadherin expression, β-catenin/Tcf and Src signaling." (PMID 25544763, 2015). "CLDN1 expression inhibited E-cadherin expression and activated β-catenin expression in colon cancer." (PMID 25544763, 2015). "Claudin-1 expression conferred resistance to anoikis in colon cancer cells in a Src-dependent manner, reduced apoposis of nasopharyngeal carcinoma cells and was also found to protect MCF-7 cells from TNF-α- and tamoxifen-induced death." (PMID 26083392, 2015). "In colon cancer, modulation of β-catenin/Tcf signaling and E-cadherin expression and localization has been shown to play an important role in claudin 1-dependent regulation of EMT." (PMID 26633531, 2015). "We employed a model that accelerates the formation of colonic tumors in APCMin mice to further examine the role of claudin-1 in tumorigenesis." (PMID 24997475, 2014).
colon carcinoma (continued). "Claudin-1 overexpression has been frequently observed in colon cancer, and mucosal inflammation, however the significance of its upregulation is not clearly understood." (PMID 24997475, 2014). "Occludin was shown to be frequently downregulated in gastrointestinal tumors and a decreased expression of claudin-1 was observed in breast and colon cancer." (PMID 24348776, 2014). "This is based on β-catenin's established importance in regulating osteoblastogenesis, as well as reports that inhibition and overexpression of Cldn-1 in a colon cancer cell line leads to a reduction and activation of β-catenin signaling, respectively." (PMID 25479235, 2014). "In support of our findings, it has been reported that inhibition and overexpression of Cldn-1 in a colon cancer cell line leads to reduction and activation of β-catenin signaling, respectively." (PMID 25479235, 2014). "Here, we show that claudin-1 overexpression in APCMin mice significantly increases colon tumor growth as well as frequency while decreasing the mice survival." (PMID 24997475, 2014). "On the other hand, Cldn-1 itself has been found to be a target for β-catenin signaling in colon cancer." (PMID 25479235, 2014). "We utilized the APCMin model of colon cancer to identify the role of claudin-1 in tumorigenesis and were able to determine that claudin-1 overexpression contributes to colon tumor growth and progression." (PMID 24997475, 2014). "Claudin-1 overexpression in APCmin mice significantly increased (~4-fold) colonic tumor growth and size, and decreased survival." (PMID 24997475, 2014). "Increased claudin-1 expression has been frequently observed in colon cancer, however the consequences of the in-vivo upregulation in colonic epithelial cells have not been investigated." (PMID 24997475, 2014). "Taken together, we concluded that claudin-1 expression aids in colon tumor progression via upregulation of the Notch- and Wnt-signaling pathways." (PMID 24997475, 2014). "As claudin-1 is a downstream target of Wnt signaling, and tumors that arise from the loss of APC have constitutive Wnt activation, we decided to examine the colonic tumors in each of these mice for potential upregulation of the Wnt/β-catenin pathway." (PMID 24997475, 2014). "Claudin-1 overexpressing colon cancer cells formed more colonies in soft agar than did control cells and increased the activity of matrix metalloproteinases (MMPs)." (PMID 24009024, 2013). "Some studies on ovarian and colon cancer report a role of CLDN1 on metastatic processes through activation of metalloproteinases, reducing apoptosis and increasing migration." (PMID 24321518, 2013). "This study also showed that claudin-1 expression increases in colon cancer, in particular in metastastic tissues with mislocalization from the cell membrane to the cell nucleus and cytoplasm." (PMID 24009024, 2013). "We postulate that claudin-1 expression and colon cancer progression correlate negatively, as previously suggested." (PMID 24069372, 2013). "In contrast, inhibition of claudin-1 expression significantly decreased the anchorage-independent growth and invasion of metastatic colon cancer cells with a significant decrease in MMP-9 activity." (PMID 24009024, 2013). "We have further shown using a large cohort of colon cancer patients that claudin-1 mRNA expression is also highly increased in colon cancer." (PMID 22719836, 2012). "Taken together, we conclude that homeodomain transcription factors Cdx1, Cdx2 and GATA4 regulate claudin-1 gene expression in human colon cancer cells." (PMID 22719836, 2012). "Irrespective, findings from our current studies demonstrates a complex regulation of claudin-1 expression, which is critically relevant to the barrier function of normal epithelial cells and oncogenic potential of the colon cancer cells." (PMID 22719836, 2012). "For this purpose, we used SW480 colon cancer cells, which express low levels of endogenous claudin-1." (PMID 22719836, 2012).
colon carcinoma (continued). "It is also worthy to note that genetic manipulation of claudin-1 expression in colon cancer cells resulted in sharp and inverse changes in their differentiation status including E-cadherin expression." (PMID 22719836, 2012). "Of interest, in addition to the dysregulated protein expression and localization, claudin-1 mRNA expression also increases in colon cancer." (PMID 22719836, 2012). "Our data supporting a significant and parallel correlation between claudin-1 and Cdx2 expression in colon cancer patient samples highlights the importance of this regulatory relationship in the regulation of colonic homeostasis." (PMID 22719836, 2012). "The expression of Claudin 1 increases during tumorigenesis of colon cancer, melanoma, oral squamous cell carcinoma and hepatocellular carcinoma." (PMID 22675434, 2012). "The increased expression of Claudin-1 in colon cancer cells resulted in increased tumor growth and metastasis in vivo, whereas the siRNA knock-down of Claudin 1 in metastatic colon cancer cells inhibited migration and invasion." (PMID 22675434, 2012). "We further provide data supporting parallel correlation between claudin-1 and Cdx2 expression in colon cancer patient samples." (PMID 22719836, 2012). "Differing data have been published concerning claudin-1 expression in colon tumors, describing both downregulation as well as overexpression of the protein." (PMID 22408413, 2012). "Claudin 1 as well as other claudins have shown in other studies a varied expression from low to elevated using immunohistochemistry in colon carcinoma depending on degree of differentiation." (PMID 23675182, 2010). "In this study we relate the expression of the tight junction proteins claudin 1 and claudin 7 and the nucleotide sequence of their genes to the complexity of the invasive border of colon carcinoma." (PMID 23675182, 2010). "An aberrant expression of tight junction proteins claudin 1 and claudin 7 in colon carcinoma compared to normal mucosa was found in this study." (PMID 23675182, 2010). "In this regard, we have recently demonstrated biological significance of altered claudin-1 expression in colon cancer cells." (PMID 20671913, 2010). "Similar dependence of claudin-1 expression in colon cancer cells upon APC and β-catenin signaling was also shown by others." (PMID 20671913, 2010). "The results show that there is a perturbed expression of claudin 1 and claudin 7 proteins in colon tumors compared to normal mucosa." (PMID 23675182, 2010). "For example increased expression of claudins 3 and 4 have been seen in ovarian and prostate cancer while claudin 1 expression has been found to be upregulated and of prognostic significance in colon cancer." (PMID 23675182, 2010). "In our studies, we observed that overexpression of claudin-1 in colon cancer cells increased activity of both MMP-2 and MMP-9 while inhibition of claudin-1 resulted in a significant decrease in MMP-9 activity." (PMID 20671913, 2010). "An important finding of our study was the nuclear localization of claudin-1 in a significant subset of colon cancer samples, particularly among the subset of liver metastatic lesions." (PMID 20671913, 2010). "CLDN1 upregulation promotes colon cancer invasion and metastasis." (PMID 40687428, 2025). "Notably, MA showed the ability to decrease claudin-1 expression, an integral membrane protein with elevated expression in metastatic colon cancer cells." (PMID 39863145, 2025). "Similarly, in colon cancer cells, Cldn1 overexpression reportedly promotes tumor metastasis through the activation of Src and β-catenin signaling." (PMID 40361399, 2025). "Nuclear localization of claudin-1 was detected in primary colon carcinomas and metastasis." (PMID 38338705, 2024).